IL6 (interleukin 6)
Diseases named in the same sentence as IL6 in open-access papers (continued):
Sharing a sentence is not in itself a finding about the gene and the disease.
infection (continued). "Infection with HTLV-1A/CoI-L resulted in low overall frequency of monocytes, DCs, and neutrophils producing IL-10, with elevated frequencies of those producing TNF-α in both compartments, linked to high expression of IL-6, CCL2, and IL-33 in blood and of MMP1, IL-1β, CCL3, and CCL19 in the lung." (PMID 41006234, 2025). "Thus, preservation of the relevant processes mediated by classic IL-6 signaling, such as infection defense, intestinal regeneration, and tissue/wound healing, could be assumed upon an exclusive inhibition of IL-6 trans-signaling." (PMID 39857830, 2025). "Furthermore, HBOT inhibits the production of pro-inflammatory factors, including interferon-γ, prostaglandins, tumor necrosis factor-α, and interleukin-6, while promoting neutrophil apoptosis at the site of infection, thereby facilitating the resolution of inflammation." (PMID 40538733, 2025). "However, IL6 knockout mice contained and controlled bacterial growth and developed a protective memory response to secondary infection, demonstrating that while IL-6 is involved in stimulating early IFN-γ production, it is not essential for the development of protective immunity against Mtb." (PMID 39963138, 2025). "In infections with “atypical” pathogens, such as C. trachomatis, an important role is played by the activation of the immune response with the production of cytokines, including interleukin-1 (IL-1), interleukin-6 (IL-6) and tumor necrosis factor-alpha (TNF-α)." (PMID 40647668, 2025). "Finally, these types of cells are involved in the host immune response through the production of tumor necrosis factor (TNF), interleukin 6 (IL-6), and cytokines in response to any infection with enveloped RNA viruses transmitted by arthropods, as is the case with CHIKV." (PMID 41472253, 2025). "Notably, IL-6 blockade with tocilizumab may offer a relatively safer infection profile compared with TNF or JAK inhibitors." (PMID 41439945, 2025). "At the local level, baseline IL-6 levels were notably higher in the lungs of uninfected females compared to males (data not presented), potentially enhancing the early immune response in females and reducing the Mtb burden during the initial stages of infection." (PMID 38999932, 2024). "The low expression of IL6 in this study may be due to the absence of infection or inflammation that causes IL6 expression in normal MSCs." (PMID 38392291, 2024). "However, IL10 secretion was induced at much lower bacterial loads as compared to IL6, indicating potential skewing towards a more anti-inflammatory response, which is consistent with the prevalent asymptomatic nature of the infection." (PMID 38808065, 2024). "If the produced IL-6 level is deficient at the acute infection response phase, the host might not defend against secondary infections." (PMID 38616284, 2024). "Moreover, hISM1-infection decreased IL-6 and TNF-α levels in aging hearts." (PMID 38300636, 2024). "Therefore, the combination of IL-6 and CRP better marker than alone IL-6 for low-grade infection." (PMID 39493345, 2024). "Correlation analyses were conducted to examine the relationship between cytokines (IL-6 and IL-10) and biochemical parameters (platelets, white blood cell count, and liver transaminases), including individuals in the two phases and with both types of infection." (PMID 39457019, 2024). "In addition, IL-6 is a key factor in the development of Th17 cells, which play important roles against bacterial infection by recruiting acute inflammatory cells into the sites of infection." (PMID 39081865, 2024). "It is important to highlight that of the different microglial phenotypes evaluated, IL-6−/− + rIL-6 brains had ≥ 75% of activated and phagocytic microglia throughout the infection and may explain the longer survival of these mice even though they showed high fungal burden early." (PMID 39334365, 2024).
infection (continued). "The secretion of IL-6 by Brucella-infected macrophages via TLR-2 contributes to activating the innate immune response against the infection; nevertheless, it could reduce the expression of class II MHC molecules (MHC-II) through a negative regulation of the transcriptional modulator CIITA." (PMID 38464511, 2024). "Generally, infection, tissue damage, or exposure to endotoxins could cause activated M1 macrophages following the production of various pro-inflammatory mediators, such as inducible nitric oxide synthase iNOS, NO, COX-2, TNF-α, IL-1β, and IL-6." (PMID 38393066, 2024). "As IL-6 classic signaling plays crucial roles in the initiation of inflammation and the host defense against pathogen infection, global blockade of IL-6 signaling may reduce the induction of hepatic acute-phase proteins upon infection, such as Listeria monocytogenes." (PMID 38890694, 2024). "Also, interleukins like IL-2, IL-6, IL-8, and IL-12 are significant modulators of the immune system: IL-2 promotes T-cell proliferation, IL-6 acts as a pro-inflammatory cytokine, IL-8 recruits neutrophils to infection sites, and IL-12 enhances the differentiation of T-helper cells." (PMID 39684540, 2024). "This infection leads to chronic inflammation, which may accelerate carcinogenesis through the secretion of proinflammatory cytokines such as TNF-alpha, IL-1β, and IL-6, which in turn increase the risk of DNA damage and mutations, which promotes the transformation of cancer cells." (PMID 39451226, 2024). "Post-infection, dietary Glut and 1% omega-3 increased intestinal interleukin-10 (IL) and secretory immunoglobulin-A and serum lysozyme, while decreased the elevated inflammatory mediators comprising interleukin IL-6, tumor necrosis factor-alpha, nitric oxide (NO) and inducible NO synthase." (PMID 38961536, 2024). "Furthermore, after infection, the human body may elicit a hyperactive immune response, resulting in the release of a substantial quantity of cytokines (interleukin-1 and IL-6)." (PMID 38435183, 2024). "Moreover, tentative anti-amoebic roles of IL-6 are still unclear, even suggesting that its upregulation during the infection could contribute, as a secondary effect, to the tissue damage observed in the brain during PAM." (PMID 38374922, 2024). "Furthermore, increased IL-6 could also discriminate infection with Escherichia and Staphylococcus at the genera level (p < 0.001)." (PMID 38672079, 2024). "Furthermore, gene expression of TNF-α, IL-1β, IL-6, and IL-8 were also significantly upregulated 1 to 5 h after infection by K. pneumoniae, although SeMet reduced inflammation and protein expression of TLR4, Ikappa-B, NF-κB, and TNF-α in bMECs and macrophages infected with ESBL E. coli." (PMID 39456758, 2024). "Moreover, a study investigating human metapneumovirus infection in children, it was found that assessing the severity and prognosis of infection may be facilitated by examining IL-6 and TNF-α expression levels." (PMID 38789583, 2024). "These experiments were verified using peripheral blood-derived macrophages, which showed similar results (Fig. 2E1, E2).Thus, acute H. pylori infection may skew macrophages to an M1 phenotype, while IL-6 (potentially as a result of long term infection) polarizes macrophages towards the M2 lineage." (PMID 38422751, 2024). "Indeed, the level of IL-6 was significantly lowered in DDX5-overexpressing MEFs and significantly increased in DDX5-deficient MEFs when compared to the controls upon infection." (PMID 38182816, 2024). "This causes the release of IL-6, IFNβ, and TNF; the latter activates pro-inflammatory pathways of NF-κB, and in this way, a vicious cycle and cytokine storm arise, recruiting immune cells (mainly T-cells in the case BoDV1 infection, although BoDV1 suppress RIG activation) to the site of infection." (PMID 38339126, 2024).
infection (continued). "After poly(I:C) infection, there was a downregulation of Uchl1 expression, while the expression of Tlr3, Caspase3, Caspase12, NOD-like receptor thermal protein domain associated protein 3 (Nlrp3), Interleukin-1β (IL-1β), IL-6, and Tumor necrosis factor alpha (Tnfα) was significantly upregulated." (PMID 38300431, 2024). "Although, the primary aim of the current study was to identify molecular changes associated with infection/inflammation in both mice and human, the concomitant increase in LCN2, CRP and IL6, that we found in this study, might aid in recognizing preterm infants experiencing infection." (PMID 37496672, 2023). "At 3 h pi the IL6 level was 177%, p < 0.0001 which increased significantly to the level 332%, p < 0.0001at 6 h and 353%, p < 0.0001 at 12 h and the level shoot-up to 682%, p < 0.0001 at 24 h post infection when compared to the level expressed at 0 h post JEV infection." (PMID 36707891, 2023). "Indeed, quantification of cytokine production by ELISA revealed a spike in secretion 6 hours post- infection with a doubling in TNF alpha levels and a fivefold increase in IL-6 levels (IL-6 average 90 pg/mL, TNFα 40 pg/mL) that were already back to baseline levels 1 day after infection." (PMID 37830871, 2023). "In general, infection induces uterine contraction, rupture of membrane, cervical softening by promoting changes in prostaglandin, matrix metalloproteinases, or oxytocin receptors through cytokines secretion and the cytokine like IL-6 activate the JAK/STAT3 signaling pathway." (PMID 38019868, 2023). "Individuals with polymorphisms in loci containing IL6, IL10, FCN2, RNASE3 and multiple Th17 pathway genes such as IL12B and IL17B had varying worm burden, indicating that these loci may play a role in determining infection intensity." (PMID 38033168, 2023). "Moreover, IL-6 in rainbow trout can induce the expression of hepcidin (an antimicrobial peptide) in macrophages by reducing iron availability, thus limiting the spread of infection." (PMID 36978643, 2023). "Interestingly, despite the unchanged level of cellular response herein detected, the decreased level of IL-6 in vaccinated group especially in patients who have received the booster dose of vaccine, highlight the protective effect of vaccination against infection." (PMID 37144176, 2023). "Furthermore, several serious infections, such as the infection caused by SARS-CoV-2, are usually associated with elevated levels of several cytokines, including interleukins IL6, IL8 and TNFα, resulting in a potential cytokine storm associated with the disease’s severity." (PMID 37446858, 2023). "We conclude that virus binding gives rise to a limited IL-6 and TNFα transitory release and that both the presence of the viral DNA within infectious particles and latent gene expression are required to reach maximal cytokine transcription and release, a process that started 2 hours post-infection." (PMID 37830871, 2023). "Our study found that IL-6 and IL-2 were increased significantly, while IL-10 was decreased in the Wheeze group, indicating that anti-(pro-)inflammatory factors imbalance may play a critical role in the occurrence and development of wheezing after infection." (PMID 36691058, 2023). "CRP, synthesized primarily by the liver in response to inflammatory cytokines (interleukin-6, interleukin-8, and tumor necrosis factor-α), is one of the most frequently used inflammatory markers in clinical practice and is released following either an infection, inflammation, or tissue damage." (PMID 37286951, 2023). "A prospective study that included 756 pediatric HLH patients found that a specific cytokine pattern with significantly elevated levels of IFN-γ and IL-10 and only moderately elevated levels of IL-6 had high diagnostic accuracy for HLH and could be used to differentiate HLH from infection." (PMID 37512867, 2023).
infection (continued). "Lower levels of circulating IL-6 among persons with T2D has been observed compared to controls, suggesting IL-6 may play an anti-inflammatory role, and that persons with T2D have a poorer inflammatory response to tissue damage and infection." (PMID 38068805, 2023). "Additionally, infections with bacteria, such as Streptococcus pyogenes, Streptococcus pneumoniae, M. tuberculosis, and T. cruzi, were more severe in IL-6−/− mice at similar inoculation titers than WT mice." (PMID 38053527, 2023). "Previous studies have demonstrated that infection of SARS-CoV-2 could induce the secretion of IL-6." (PMID 38107861, 2023). "The broad range of TNFα, IL-6, and IFNα responses seen among the IAV patients suggest that seasonal IAV strains are associated with milder cytokine responses than those observed during infections with 2009 H1N1 pandemic influenza or highly pathogenic avian H5N1 strains." (PMID 36752598, 2023). "Prior studies of cytokines in blood have found that IL-6, IL-10, and TNF-α increase in burn compared to healthy pediatric patients, that elevated circulating TNF-α is associated with death, and that decreased circulating TNF-α/IL-10 ratio is correlated with an increased chance of infection." (PMID 36790939, 2023). "Hence, it plausible that with a less virulent infection, maternally‐derived IFNγ may be a more prominent driver of the HSC response, whereas with more virulent infections other cytokines, such as IL‐6 and IL‐1α, may further impact HSC function." (PMID 37259639, 2023). "Furthermore, the levels of IL6 changed significantly over the 6 week period in the infection group (p = 0.004) and the levels of TNFα also showed significant changes over the weeks in the healthy group (p = 0.013) and in the infection group (p = 0.0098)." (PMID 37762523, 2023). "Therefore, the comparison between mice strains shows that BALB/c mice have higher values of the proinflammatory cytokines (IFN-γ and IL-6) and the anti-inflammatory cytokines (IL-10 and IL-4) in response to infection than C57BL/6 mice (Welch two-sample t test, P < 0.05)." (PMID 37140369, 2023). "Our findings also confirmed that T. gondii Wh6 infection upregulated the expression of IL-6, TNF-α and IL-1β in the PFC region, which was restricted by β-glucan, suggesting that the neuroinflammation and cytotoxicity of hyperactivated glial cells could be reduced by β-glucan." (PMID 36782332, 2023). "Inflammation is closely related to immunity, and infection evokes the body's immune response, leading to the stimulation of the host cell immune signaling pathway, promoting the inflammatory response, and increasing the release of IL-6 pro-inflammatory factors." (PMID 37180342, 2023). "The defect in parasite development in IL-6 transgenic SPZ-infected mice which are completely refractory to infection even after multiple challenges with high doses of SPZ predicts that elicitation of T cells upon a successful vaccination regimen might have taken place in these mice." (PMID 37143657, 2023). "Therefore, greater resistance to IL-6-mediated immune responses can provide a selective advantage during invasive infections and is encoded by M1T1 GAS but not M4." (PMID 37874162, 2023). "For instance, the production of tumor necrosis factor (TNF) α and interleukin-6 (IL-6), after TLR1/2 engagement, was down-regulated in older adults, compared with younger populations, suggesting that diminished TLR1/2 signaling contributes to an increased risk of infection in older adults." (PMID 36808423, 2023). "However, in some cases, due to the biphasic bacterial cycle, deviation in the immunological response towards the Th2 profile (increased levels of IL-4 and IL-6), which correlates to a poor infection prognosis, may occur." (PMID 36897879, 2023).
infection (continued). "In addition to the 72 hpi timepoint used for RNA-seq, we found that infection with so/sp Mtb elicited significantly higher levels of expression of Il1b, Nos2, Il6, and Tnf at 6 and 24 hpi by qPCR compared with 5μmF preparations, with the greatest difference seen early in infection." (PMID 36852737, 2023). "However, infection of IL-6−/− mice with WNV Eg101 resulted in 60% mortality." (PMID 38053527, 2023). "Transcripts encoding the inflammatory cytokines, TNF-α, IL-1β and IL-6, were not consistently detected in monolayers subjected to mock infection with medium alone, but infection with all of the DENV isolates stimulated IL-6 expression, although notably higher levels were seen with DENV2 strains." (PMID 37515098, 2023). "In the present study, we have evidence that, besides infection, the bystander activation of microglia through inflammatory mediators secreted by Brucella-infected astrocytes can also induce such a phenomenon and that IL-6 is essential for the phagocytosis of neurons to take place." (PMID 38322014, 2023). "The IL-6/STAT3 axis is heavily involved in the pathogenic process of SARS-CoV-2 infection, and some researchers suggest that modulation of this pathway could be an important target for pharmacological therapy against the infection." (PMID 36834984, 2023). "Moreover, we found that infection with SADS-CoV induced mRNA expression of inflammatory cytokines such as IL-6, IL-1β, and TNF-α, all of which could be prevented by 17-DMAG." (PMID 36963723, 2023). "CRP and IL-6 might serve as independent factors prewarning the severe infection occurrence." (PMID 35037900, 2022). "Specifically, IL-1β and IL-6 expression was significantly increased at 1 dpi, and IL-6 sustained the high expression level up to 3 dpi, which suggests that IL-1β plays a crucial role in the response to infection by Zika virus as well as other flaviviruses, WNV and JEV." (PMID 36069671, 2022). "IL-6 is a pleiotropic cytokine with a wide range of functions, which can regulate the growth and differentiation of a variety of cells, regulate immune response, acute phase response and hematopoietic function, and plays an important role in the body’s anti- infection immune response." (PMID 35549778, 2022). "Additionally, hepcidin expression increases in response to infection and inflammation as part of the body's acute phase response, with the cytokine Interleukin-6 (IL-6) the main stimuli responsible for limiting iron availability for bacterial growth and viral replication." (PMID 35966107, 2022). "HIV-infected children have also been noted to accumulate bone density more slowly than non-infected children through direct infection of bone cells causing elevation of several cytokines (interleukin 1, interleukin 6, and tumor necrosis factor-α) that contribute to increased activity of osteoclasts." (PMID 36199047, 2022). "Guan’s study did not observe the significance of the combination of IL-6 and IL-10 for the differentiation of G- and G+ infection, which may be caused by factors such as the different types of diseases of the study subjects." (PMID 35432366, 2022). "Inflammatory cell infiltration in the lamina propria was detected in the intestine of P. vivax-infected pigeons as early as 2 dpi, which could be related to the higher expression of inflammatory cytokines (IL-1, IL-6, and IL-18) in the intestine during early infection." (PMID 36187827, 2022). "Interleukin-6 (IL-6) is responsible for the innate and acquired immune response and also several other activities during the improvement of acquired immunity against infections, while also responsible for antibody fabrication of B cells and differentiation of dendritic cell and T cell regulations." (PMID 36421668, 2022).